HDAC3 (histone deacetylase 3)
Diseases named in the same sentence as HDAC3 in open-access papers (continued):
Sharing a sentence is not in itself a finding about the gene and the disease.
cancer (continued). "For example, Entinostat (MS-275), which is currently in clinical trials for cancer treatment, selectively inhibits HDAC1, HDAC2, and HDAC3 with an IC50 of 0.54, 0.61, and 0.62 μM, respectively." (PMID 37759724, 2023). "On the other hand, the network of RGFP-966, which targets HDAC3 selectively, is topologically distant from other HDAC inhibitor networks in different cancer types." (PMID 35440787, 2022). "From drop-out screens in multiple cell lines, we identified novel epigenetic modifiers for cancer cell fitness as well as the previously studied ones such as PRMT5, HDAC3, FOXA1 and LSD1." (PMID 35973998, 2022). "Some bioinformation analysis of data download from cancer databases regarding FOXA1 and HDAC3 expression should be added in the further analysis." (PMID 34991620, 2022). "We also performed real-time PCR (RT-PCR) with cDNAs from human STS samples and analyzed the clinical significance of class I HDAC expression including HDAC1, HDAC2 and HDAC3, in 49 patients with different subtypes of STS treated at our cancer center." (PMID 33637599, 2021). "In cancer cells with drug resistance, decreased COP1 enhanced JNK/c-Jun signaling activation, consequently inhibiting histone deacetylase 3 (HDAC3) expression." (PMID 34088360, 2021). "Histone deacetylase 3 (HDAC3) plays an important role in signal-dependent transcription and is dysregulated in diseases such as cancer." (PMID 34520758, 2021). "We explored here the expression profile of HDAC family via Oncomine database, which indicated that HDAC1, HDAC2, HDAC3, HDAC7, HDAC8, and HDAC9 expressed highly in pan‐cancer at transcriptional level." (PMID 34308568, 2021). "Taken together, our data demonstrated that HDAC3 is functional responsible for USP38 mediated histone modifications, which further controls the expression of cancer stem cell-related genes." (PMID 32404892, 2020). "Downregulation of USP38 led to ubiquitination of HDAC3, which resulted in decreased acetylation levels of H3K27 in the promoter regions of cancer stem cell related genes." (PMID 32404892, 2020). "One of these, the class I HDAC inhibitor entinostat (HDAC1>HDAC3), was previously shown to restore SLFN11 expression and sensitivity to DNA damage in resistant cancer cell lines." (PMID 31632920, 2019). "Single knockdown of HDAC1, HDAC2, HDAC3, LSD1, DNMT1, and EZH2 generated different effects of neuron-like differentiation in cell lines of different cancer types." (PMID 31130994, 2019). "The interaction between HDAC3 and PIWIL2 has great effects on HDAC3-mediated epigenetic regulation and cell proliferation on cancer." (PMID 30886064, 2019). "Our results suggest that HDAC3 is an important regulator of STAT3-dependent cell proliferation in liver regeneration and cancer." (PMID 29540666, 2018). "Thus, HDAC3 may confer sensitivity to anti-cancer drugs by regulating expression of SIAH2." (PMID 30583572, 2018). "However, how HDAC3 is regulated in cancer remains largely unknown." (PMID 29555935, 2018). "The MiR-326 inhibitor increases the expression of HDAC3, which results in the binding of HDAC3 to promoter sequences of CAGE in anti-cancer drug-resistant Malme3MR cells." (PMID 30583572, 2018). "In order to evaluate the in vivo anti-cancer effects of HDAC3 inhibition, we employed a CCA tumor xenograft model and found that HDAC3 knockdown cells also showed a low proliferative capacity and tumorigenicity compared to their counterparts." (PMID 29245911, 2017). "Histone deacetylase 3 (HDAC3) has an oncogenic role in apoptosis and contributes to the proliferation of cancer cells." (PMID 28569784, 2017). "The best characterised and probably biologically most relevant HDAC in human cancers are class I isoforms HDAC1, HDAC2, and HDAC3." (PMID 28785170, 2017).
cancer (continued). "The role of individual histone deacetylases (HDACs) in the regulation of cancer cell proliferation was investigated using siRNA-mediated knockdown (HDAC1, HDAC2, HDAC3, HDAC4 and HDAC7) in HeLa cells." (PMID 26560874, 2016). "To examine the mechanism through which the reduction of HDAC3 activity takes place, we determined the protein levels of class I HDACs and PARP-1 in delphinidin-treated cancer cells using western blot analysis." (PMID 27462923, 2016). "Previous studies have demonstrated that the class I and II histone deacetylases (HDACs), including HDAC1, HDAC2, HDAC3 and HDAC4, repress p21 expression in multiple human cancers." (PMID 26098774, 2015). "To expand our studies on the role of HDACs in ATX expression, we examined expression levels of HDAC3, HDAC7 and ATX in 13 cancer cell lines." (PMID 21314984, 2011). "Collectively, our data indicate that HDAC3 and HDAC7 play a critical negative regulatory role of in ATX expression, and serve as TSA targets in the ATX induction in cancer cells." (PMID 21314984, 2011). "The target protein(s) of HDAC3/HDAC7 involved in ATX expression regulation remains to be identified, which will be helpful to explain why TSA cannot induce ATX expression in a few cancer cell lines including HT-29, LNcap and Jurkat cells." (PMID 21314984, 2011). "Reducing NCOR2 expression or preventing its interaction with Histone Deacetylase, HDAC3, enhances innate immune cell recruitment and activity, and elevates MHC class I levels on disseminated cancer cells to potentiate CD8+ T cell activity and apoptosis induction that prevents metastatic progression." (PMID 42086546, 2026). "Targeting KCa3.1 and LRRC8A, along with pathways such as WNK1–AMPK–p38 MAPK and HDAC3, may provide new therapeutic avenues to reeducate and reprogram TAMs within the TME, thereby enhancing the efficacy of cancer immunotherapy." (PMID 40806751, 2025). "The coordinated inhibition of HDAC6, HDAC3, and HDAC4 by BKS-112 may synergistically contribute to its potent anticancer effects, as these isoforms play distinct but complementary roles in cancer cell survival and progression." (PMID 41300448, 2025). "Histone deacetylase 3 (HDAC3) is a member of the histone deacetylase family that has emerged as a crucial target in the quest for novel therapeutic interventions against various complex diseases, including cancer." (PMID 39005934, 2024). "Considering that the critical functions of HDAC3 in human cancers including LUAD are still not fully interpreted and the important findings were observed in this study, we further revealed the important role of HDAC3 in LUAD through cell function experiments." (PMID 37553641, 2023). "miR24‐2 inhibits histone deacetylase HDAC3 through miR675 to promote histone H4K16ac, which acts on PI3K and enhances the interaction between LC3 and ATG4, consequently triggering autophagy that affects cancer cell proliferation." (PMID 37143582, 2023). "In A549, knockdown of HDAC3 could significantly inhibit malignant biological behaviors such as cell proliferation, migration, and invasion, indicating an oncogenic function of HDAC3 in LUAD, which was consistent with it in other cancer types." (PMID 37553641, 2023). "A wealth of evidence indicates that HDAC3 inhibitors such as RGFP966, MI-192, and BG45 may hold promise for treating various diseases, including cancer." (PMID 38034086, 2023). "HDAC3, HDAC10, HDAC2, HDAC7, ATAD2B were significantly upregulated in 9, 14, 13, 9, and 10 cancer types, respectively, whereas KAT2B was downregulated in 16 cancer types." (PMID 37553641, 2023). "Several HDACs can act to deacetylate a certain histone in different forms of cancer: H3K9 (HDAC3), H3K14 (HDAC1, HDAC3), H3K56 (HDAC1, HDAC2), H4K5 (HDAC1, HDAC2, HDAC3), H4K8 (HDAC1, HDAC2), H4K12 (HDAC1, HDAC2, HDAC3), and H4K16 (SIRT1, SIRT2, HDAC1, HDAC2, HDAC3)." (PMID 36614156, 2022).
cancer (continued). "HDAC3, the unique HDAC isoform that binds to the nuclear receptor corepressor NCOR1/SMRT, has been revealed to play a specific role in the emergence and development of cancer." (PMID 35910736, 2022). "Conversely, negative PD-L1 regulators (HDAC1, HDAC2, and HDAC3) seemed insignificant during cancer progression." (PMID 34830209, 2021). "We also followed up on the unexpected observation that HDACi inhibiting HDAC1/2, but not HDAC3 lead to accumulation of UC cells in G2/M phase, whereas HDACi treatment of many other cancer cell entities—solid and hematopoietic—usually results in G1 arrest." (PMID 33670166, 2021). "Overexpression of HDAC1, HDAC2, HDAC3, and HDAC6 has been reported in different cancers." (PMID 35096000, 2021). "Some studies support our results, showing that increased expression of autotaxin in PCa cell lines is mediated by the downregulation of HDAC7 and HDAC3; additionally, HDAC5 is downregulated in human cancer, namely PCa, and decreased expression of HDAC4 increases the growth of PCa cells." (PMID 34833128, 2021). "In our study, c-Jun knockdown upregulated HDAC3 expression in drug-resistant cancer cells, which indicates the role of negative c-Jun regulation in HDAC3 expression." (PMID 32024543, 2020). "Thus, our results indicate that HDAC1 and HDAC3 epigenetically suppress the expression of Snail2 during the EMT of liver cells, revealing an opposing function of HDACs during the migration of malignant tumors." (PMID 32850856, 2020). "HDAC3 forms a negative feedback loop with miR-326 and enhances sensitivity to anti-cancer drugs in vitro and in vivo." (PMID 32626712, 2020). "Both HDAC3 and HDAC6 could increase the expression of survivin and siRNA treatment of HDAC3 and HDAC6 showed a similar effect of SAHA and induced autophagy in MCF7 and MDA-MB-231 cancer cells." (PMID 33193750, 2020). "The recruitment of HDAC3, as well as the suppression of cancer metastasis by CBX4, are neither dependent on its chromodomain nor its PRC1 complex." (PMID 32111827, 2020). "Therefore, HDAC3 can target CAGE to regulate the activation of EGFR signaling, responses to various anti-cancer drugs, and the tumorigenic potential of cancer cells." (PMID 30583572, 2018). "HDAC3, a member of the class I HDAC family, is overexpressed in many cancer cells." (PMID 29555935, 2018). "This has led us to investigate relationships between HDAC3 and CAGE in anti-cancer drug resistance." (PMID 30583572, 2018). "Among them, HDAC1, HDAC3, and LSD1 were barely expressed in hiPSCs and normal somatic cells (fibroblasts and T-lymphocytes), but they were strongly expressed in hiPSC-derived teratomas and cancer cell lines (K562, HeLa and HEK293) at the protein level." (PMID 29464084, 2018). "However, most of them belong to anti-cancer pan-HDAC inhibitors and rarely show specific inhibition for HDAC3." (PMID 28106794, 2017). "miR-326, which is increased in anti-cancer drug-resistant cancer cells, regulates the response to anti-cancer drugs by forming a negative feedback loop with HDAC3." (PMID 26863629, 2016). "In Ad-ZBP-89-infected Pin1+/+ cancer cells, Pin1 siRNA increased HDAC3 but decreased Bak, compared with cells without ZBP-89 infection." (PMID 25623232, 2015). "Thus, we conclude that HDAC3 plays a distinct role from HDAC1 and HDAC2 during chromatin maturation and that targeting HDAC3 with small molecule inhibitors will provide additional therapeutic impact in the treatment of CTCL and other cancers." (PMID 23894374, 2013). "We have demonstrated that ATX expression is repressed by HDAC3 and HDAC7 in cancer cells." (PMID 21314984, 2011). "In the present paper, we demonstrated a novel ATX expression regulation mechanism in cancer cells, in which HDAC3 and HDAC7 were involved as negative regulators." (PMID 21314984, 2011). "HDAC3 and HADC7, as the targets of TSA, were involved in ATX expression regulation in cancer cells." (PMID 21314984, 2011).
cancer (continued). "Therefore, Apigenin may act as a potent inhibitor of HDAC1 and HDAC3 in a fashion like SAHA and can be used as an anti-cancer agent for the treatment of TNBC patients." (PMID 38664447, 2024). "For example, hypoxia-induced histone deacetylase 3 represses lncRNA-LET by reducing the histone acetylation-mediated modulation of the lncRNA-LET promoter region, which leads to the stabilization of nuclear factor 90 protein and hypoxia-induced cancer cell invasion." (PMID 33407675, 2021). "Therefore, the effects of CBX4 on Runx2 are different among cancer cell types, depending on the cellular ratio of GCN5 to HDAC3, and subsequently CBX4 may promote or inhibit metastasis depending on the cancer type." (PMID 32111827, 2020). "Interestingly, cMyc and HDAC3 constitutes a positive feedback loop, which is connected by pyruvate: cMyc decreases pyruvate levels by promoting PKM2 and LDHA levels, consequently decreasing inhibition to HDAC3 and protecting cancer cells from apoptosis." (PMID 30866966, 2019). "miR-326 forms a negative feedback loop with HDAC3 and regulates the response to anti-cancer drugs." (PMID 26863629, 2016). "Inactivation of HDAC3 is sufficient to trigger apoptosis in cycling, non-quiescent murine embryonic fibroblasts, suggesting that HDAC3 could be a therapeutic target in highly proliferative cancer cells." (PMID 24904826, 2014). "Knockdown of HDAC3 had no impact on HDAC9 expression, but readily induced BRM and caused BRM-dependent growth inhibition, which paralleled our observations in the non-Rhabdoid BRM-deficient cancer cell lines SW13 and C33A." (PMID 24913006, 2014). "Indeed, to achieve this goal and consideringthe pathological role played by HDAC3 in cancer and noncancerous diseases,researchers further investigated the influence of decorating the capgroup of N-propyl/N-butyl hydrazide-basedHDACi to obtain HDAC3-selective derivatives." (PMID 40637413, 2025). "Unlike PD-L1 negative regulators (HDAC1, HDAC2, and HDAC3), the expression ranks of PD-L1 and its positive regulators (EP300, CREBBP, IRF-1, and BRD4) negatively correlated to Grade Group in another study, suggesting an increase of function during cancer progression." (PMID 34830196, 2021). "Interestingly, targeting HDAC3 and HDAC6, but not other HDAC isoforms, by siRNA/pharmacological inhibitors mimicked the effects of SAHA in modulating the acetylation, expression, and nuclear translocation of survivin and induced autophagy in MCF7 and MDA-MB-231 cancer cells." (PMID 27065869, 2016).
tumor (186 papers, 2008 to 2026). "Since tumor occurrence is closely linked to abnormal metabolic activities and unpredictable strong inflammatory responses, HDAC3 has attracted increasing exploration and attention as a target for tumor treatment strategies." (PMID 40006729, 2025). "And HDAC3‐deficient HCC cells recruited CXCR3+ T cells into the tumor microenvironment to inhibit tumor growth." (PMID 38783893, 2024). "Genes disturbed by CREBBP mutation are direct targets of the BCL6/SMRT/HDAC3 tumor–repressor complex." (PMID 36831561, 2023). "The results from clinical tissues analysis reveal that HDAC3 overexpression is associated with tumor recurrence and poor prognosis." (PMID 34973135, 2023). "The interaction between HDAC3 and cancer-associated genes influences the angiogenic and carcinogenic potential of tumours and the efficacy of antitumour drug treatment." (PMID 34395273, 2021). "HDAC3 activity is a key factor for the maintenance of the expression of these tumor- and stemness-associated transcription factors in AML cells." (PMID 31561534, 2019). "Taken together, these results suggest that following cell-autonomous tumor cell death caused by HDAC3 inhibition, residual tumor cells under chemotherapeutic stress are induced to express cytokines and growth factors." (PMID 31113472, 2019). "Our data demonstrate that HDAC3 activity is a key factor for the survival and the maintenance of tumor- and stemness-associated transcription factors in AML cells." (PMID 31561534, 2019). "High expression levels of HDAC-3 were only associated with higher tumour grade according the new WHO 2004 grading system." (PMID 24624923, 2014). "Interestingly, higher HDAC3 expression is associated with lower tumor grade and better patient survival." (PMID 40940748, 2025). "Accordingly, we propose that assessing IκBζ protein levels in tumor biopsies could serve as a diagnostic strategy to identify patients who would benefit from a combined immunotherapy with HDAC3 or EZH2 inhibitors." (PMID 40562773, 2025). "Besides, it can also decrease the expression of histone deacetylase 3 (HDAC3) causing a decline in tumor progression." (PMID 39210613, 2024). "Compared with normal tissues, the expression of CNV-amplified HA regulators was significantly increased in tumor tissues (e.g. HDAC3 in KIRC), while the expression of CNV-deficient HA regulators was significantly decreased (e.g. KAT2B, HDAC11 and PBRM1 in KIRC)." (PMID 37553641, 2023). "Histone deacetylase 3 (HDAC3) governs lncRNA-LET (low expression in the tumor), which may be implicated in hypoxia-induced cell death." (PMID 36004931, 2022). "The univariate results of Cox regression analysis showed that increased tumor size/histological grade/lymph node invasion/HDAC1/HDAC2/nuclear HDAC3/cytoplasmic HDAC3 were significantly associated with shorter overall survival, while positive ER or PR was associated with prolonged overall survival." (PMID 32686908, 2020). "The associations between HDAC1/HDAC2/HDAC3 and classical clinicopathological characteristics such as age, tumor size, histological grade, lymph node status, ER, PR, HER2, brain metastasis and molecular subtypes were analyzed by Spearman's rank‐correlation test and χ2 test." (PMID 32686908, 2020). "HDAC3 inhibition induces apoptosis and disrupts tumor-associated protein expression." (PMID 31561534, 2019). "Furthermore, overexpressed HDAC3 was further associated with increased tumor growth and a poor prognosis in HCC patients." (PMID 29540666, 2018). "Additionally, overexpression of HDAC3 is associated with advanced tumour stage and early recurrence post-surgery." (PMID 29079534, 2017). "It is worth noting that elevated HDAC3 levels are a common hallmark of tumour cells." (PMID 26450925, 2015).